STAT3 (signal transducer and activator of transcription 3)
Diseases named in the same sentence as STAT3 in open-access papers (continued):
Sharing a sentence is not in itself a finding about the gene and the disease.
viral infection (continued). "For example, CPV can trigger host G1/S cell cycle arrest via the EGFR (Y1086)/p27 and EGFR (Y1068)/STAT3/cyclin D1 axis, and in the late stage of viral infection, nuclear assembly of the progeny capsids is accompanied by virus-induced cell cycle triggering host cell G2/M phase arrest." (PMID 38384266, 2024). "These targets include STAT3, which is a key regulator of the host's innate response to viral infections, IFNAR1, a vital antiviral factor, MDA5, an RNA antiviral sensor, and protein kinase TBK1, which participates in the induction of type I interferons in response to viral replication." (PMID 38501860, 2024). "STAT3 has a protective role at the early stage of several viral infections." (PMID 39201692, 2024). "STAT3 has been documented to play important roles in viral infection and pathogenesis." (PMID 37378295, 2023). "TYK2 also interacts with STAT3, which is vital to virus infection." (PMID 37371627, 2023). "STAT1/STAT3 heterodimerization is favoured by IL-27 during viral infections such as HBV and HSV, and may represent an alternative pathway to ISG production, as the STAT1/STAT3 heterodimer is not typically associated with IFN signaling." (PMID 35634328, 2022). "The JAK2 and IL6/JAK2/STAT3 signaling pathways are therapeutic targets for treating excessive inflammatory response to virus infection, where PIK3CB, the target of miRNA−34a participated in TCR−mediated NF−κB signaling after binding to B7 ligand on antigen presenting cells (APC)." (PMID 36298658, 2022). "Although the mRNA of STAT3 was up-regulated in our data—likely as a response of the cell to the viral infection—its protein levels may be severely impacted, as TNK2-AS1 was one of the most down-regulated genes of the network." (PMID 36362378, 2022). "However, in the setting of human diseases, STAT3 SNP analysis appears to be important and practical for studies of cancers and virus infections/diseases." (PMID 34307193, 2021). "Using IFNα/β to mimic the antiviral response induced by virus infection, we found similar changes of STAT3 and PKR which indicated that the abrogation of the antiviral response by β-blocker could be caused by virus induced secretion of type I IFN." (PMID 34544479, 2021). "The hyperactivation of NF-κB and STAT3 pathway either as a result direct viral infection or elevated Angiotensin 2 (AngII) in serum may result in CRS." (PMID 33757410, 2021). "STAT3′s role has been well characterized in the pathogenesis of viral infections." (PMID 34071096, 2021). "Taken together, these results reveal that SOCS3 might play a crucial role not only in suppressing IL-6/STAT3 signaling but also in feedback regulation of IL-6 expression during the viral infection." (PMID 31474976, 2019). "Furthermore, pIL-11 was found to inhibit viral infection by preventing PEDV-mediated apoptosis of cells by activating the IL-11/STAT3 signaling pathway." (PMID 31864417, 2019). "The antagonism between STAT1 and STAT3 seems to be cell type-specific or specific to a certain gene locus, as a cooperation between STAT1 and STAT3 downstream of IL-6 has been described for optimal Bcl6 induction and Tfh differentiation in response to viral infections." (PMID 31998303, 2019). "STAT3 also exhibits dual regulatory roles during viral infection." (PMID 31575039, 2019). "Due to the high requirement of the regulation in CNS immune response, we speculate that the tightly regulated STAT3 targets contributed to a fine-tuned antivirus status in glia cells to avoid overreaction and tissue damage post viral infection." (PMID 31575039, 2019). "However, in some circumstances, STAT3 has an antiviral function in other viral infections, such as enterovirus 71, severe acute respiratory syndrome coronavirus and human metapneumovirus." (PMID 32201498, 2018). "Recently, the role of STAT3 in viral infection has been attracting research interest." (PMID 32201498, 2018).
viral infection (continued). "However, on the basis of the present data, we conclude that the host STAT3 signaling responses to virus infections are complicated and it would be regulated in a virus-specific manner and even with a stage-specific characteristic in the virus life cycle." (PMID 32201498, 2018). "Recent studies have shown that STAT3 plays important roles in viral infection and pathogenesis." (PMID 32201498, 2018). "However, targeting STAT3 during viral infection and cancer is currently an untapped reservoir, and the question still remains as to why it has not yet resulted in a broad range of clinical applications." (PMID 29543893, 2018). "Several studies reported differential regulation of STAT3 in a range of viral infections." (PMID 26199948, 2015). "STAT3 role in viral pathogenesis appears to be complex with reports suggesting both promotion of innate antiviral response and contribution to the detrimental effects of viral infection." (PMID 26199948, 2015). "It is possible that the timing of STAT3 regulation during virus infection may be critical and hence require further in depth studies to profile STAT3 regulation during different stages of viral infection." (PMID 26199948, 2015). "Hence, following acute viral infection, STAT-3 has been reported to repress Type I interferons to promote Tfh cell differentiation, at the cost of Th1 polarization." (PMID 26501424, 2015). "STAT-3 over expression in chicken cells or inhibition in duck cells had no significant (p > 0.05) effect on the expression of IFN-α expression following H5N1-tyEng91 virus infection." (PMID 25431115, 2014). "However, the relationship between STAT3 and lncRNAs during viral infection is poorly understood." (PMID 41208976, 2025). "On the other hand, it has been shown that STAT3 could promote some viral infections." (PMID 41208976, 2025). "Notably, even under the same viral infection context, STAT3 may switch between pro-viral and anti-viral functions depending on the specific physiological conditions of the host." (PMID 41488475, 2025). "Like STAT3-HIES, patients with DIDS have the classic features of high IgE, eosinophilia, severe AD, skin infections (abscess), and CMC, but are distinguished by an increased propensity for cutaneous viral infections and increased risk for autoimmunity and malignancy." (PMID 41181176, 2025). "Thus, we postulated that IL6/STAT3 signaling might regulate HSP90 expression to engage in viral infection." (PMID 37099596, 2023). "However, several studies have reported differential regulation of STAT3 in viral infections." (PMID 36483552, 2022). "STAT3 has on the other hand been pointed out as factor of major importance in the pathogenesis of gastrointestinal bacterial infections and cancer development along with viral infectious diseases (HBV, HCV and HPV) which in turn may drive cancer development." (PMID 34630328, 2021). "Also, STAT3 pathway is upregulated in several other viral infections." (PMID 33529218, 2021). "In our SARS-CoV-2 infected iPSC-derived acinar cells, we believe CXCL12 could be playing either pro-inflammatory roles since other known pro-inflammatory transcription factors were also upregulated, such as NKFB1 and STAT3, or a defensive anti-inflammatory defensive to viral infection." (PMID 34282405, 2021). "SOCS1 and SOCS3 may promote virus infection by inhibiting IFN-induced STAT3 phosphorylation." (PMID 32149091, 2020). "However, the mechanism of actions by STAT3 during viral infection remains poorly understood." (PMID 31575039, 2019). "Since our results presented above exhibited that IL-6-activated STAT3 was inhibited by IAV-induced SOCS3 and knockdown of SOCS3 downregulated IL-6 during the viral infection, we asked whether elevated activity of STAT3 caused by silencing SOCS3 affected IL-6 expression." (PMID 31474976, 2019). "Therefore, the suppression of IL-6/STAT3 signaling by elevated SOCS3 induced by IAV might contribute to excessive production of IL-6 during the virus infection." (PMID 31474976, 2019).
viral infection (continued). "Given that STAT3 activation could be triggered by different virus proteins or virus-induced host factors, and specific kinase members would be recruited to activate STAT3 after different virus infection, the downstream target genes regulated by STAT3 must be distinctive." (PMID 32201498, 2018). "Therefore, we investigated whether the increase in NEAT1 expression induced by viral infection is mediated by STAT3." (PMID 27783096, 2017). "Many of these transcription factors, such as NF-κB, STAT3, and HNF4A, are known to be activated in response to viral infections and inflammation." (PMID 40408617, 2025). "Similar mechanisms have been observed in other viral infections, such as HIV and influenza, where the virus-induced activation of STAT3 signaling contributes to viral replication and immune evasion." (PMID 40143240, 2025). "STAT3, a downstream effector molecule of various cytokines and growth factors, typically inhibits IFN-I antiviral activity and facilitates viral infection." (PMID 40128890, 2025). "As a means to assess whether the JAK2/STAT3 signaling pathway may contribute to depressive‐ and anxiety‐like behaviors in miR‐204‐5p deficient rats, we injected SC99 or WP1066, the JAK2/STAT3 signaling pathway inhibitor, for 7 days after virus infection 2 weeks in miR‐204‐5p knockdown rats." (PMID 39792918, 2025). "Viral infections interact mainly with the activated Signal Transducer and Activators of Transcription 1, 2, and 3 (STAT1, STAT2 and STAT3) to release pro-inflammatory cytokines to eliminate viruses." (PMID 38628843, 2024). "Resveratrol affects the phosphorylation status of STAT3 and indirectly downregulates the level of MCL-1 in HTLV-positive ATLL cells, abolishing the prosurvival effect of viral infection." (PMID 38256213, 2024). "Signal transducer and activator of transcription 3 (STAT3), a member of the STAT family, plays a critical role in transmitting extracellular signals to the nucleus, governing inflammation, combating viral infections, and regulating antitumor immune responses." (PMID 37669923, 2023). "To determine and validate the role of temperature on viral infection and IL6/STAT3 signaling, we firstly evaluated the effect of temperature-switch on the immune responses of grass carp tissues or CIK cells." (PMID 37099596, 2023). "The most important was that the previous study defined STAT3 as a negative regulator of type I IFN response, and provided a therapeutic target for viral infections." (PMID 37924089, 2023). "During acute viral infection, IL6 activates both Stat1 and Stat3, with the latter being required to limit IL2/Stat5-induced Th1 differentiation." (PMID 37275873, 2023). "On the other hand, the persistent inflammation sustains the activation of signal transducer and activator of transcription 3 (STAT3), further promoting HCV replication and thus enhancing viral infection." (PMID 35681679, 2022). "This indicates that the STAT3 and type I IFN signaling pathways have an opposite role in Tfh development following viral infection." (PMID 32999454, 2021). "Activation of signal transducer and activator of transcription 3 (STAT3) is a well-known host response in various bacterial and viral infections." (PMID 33785629, 2021). "Phosphorylated STAT3 can inhibit IRF1 transcriptional activation and thus represses the induction of IFNs upon viral infection." (PMID 30735121, 2019). "So far, serine monophosphorylation induced by virus infection has been only reported for STAT1 and STAT3." (PMID 29662014, 2018). "To date, serine mono-phosphorylation induced by virus infection has only been reported in STAT1 and STAT3." (PMID 29312301, 2017). "High expression of p-STAT-3 protein in chicken cells over-expressing pSTAT-3 and reduced p-STAT-3 expression in duck cells treated with S3I-201 at 24 h following virus infection was detected by western blotting." (PMID 25431115, 2014).
viral infection (continued). "Chicken cells transiently transfected with phospho-STAT-3 showed a significant (p < 0.05) reduction in LITAF, IL-6 and IL-8 mRNA expression following 24 h of H5N1-tyEng91 virus infection." (PMID 25431115, 2014). "Duck cells treated with S3I-201 that inhibits the transcriptional activity of STAT-3, resulted in increased expression of LITAF, IL-6 and IL-8 compared with control cells at 24 h post H5N1-tyEng91 virus infection." (PMID 25431115, 2014). "Chicken cells over-expressing constitutively active STAT-3 showed significantly lower LITAF, IL-6 and IL-8 mRNA levels compared with the blank plasmid transfected cells at 24 h post H5N1-tyEng91 virus infection." (PMID 25431115, 2014). "STAT3 can be activated by IL-6 and interferon-gamma (IFN-γ) by viral infection." (PMID 40006981, 2025). "This non-transcriptional functional diversity of STAT3 is closely intertwined with viral infection processes." (PMID 41488475, 2025). "Previous studies have theorized that hsa-miR-146a is overexpressed in many viral diseases, targeting and inhibiting specific genes, such as STAT1, SOCS1/STAT3, TCL1, CXCL4, and NFκB in hepatitis B and C, EBV, human immunodeficiency type-1, and human T-lymphotropic type 1, respectively." (PMID 37233676, 2023). "To date, there is no report of the interplay between temperature, IL6/STAT3 signaling, and aquatic virus infection." (PMID 37099596, 2023). "Initially, STAT3-HIES was suspected in this patient due to HIES clinical phenotype (NIH score 46) in the absence of severe viral infection and food allergy." (PMID 36703986, 2022). "IFN‐I can activate the STAT3/4‐granzyme B pathway in tumor‐infiltrating CD8+ T cells, inhibit tumor growth, and directly maintain the clonal expansion of CD4 T cells to fight virus infection." (PMID 35253368, 2022). "Signal transducer and activator of transcription 3, a major oncogenic transcription factor involved in cancer development and progression, is regulated by GRIM19 in some tumor cell lines, but little is known regarding their relationships in viral infections." (PMID 28443075, 2017). "While STAT-3 expression was not significantly affected (P > 0.05) by LPAI H2N3 virus infection, its expression was significantly reduced to half as much (P < 0.05) by H5N1-tyEng91 or H5N1-tyTR05 virus in infected chicken cells." (PMID 25431115, 2014). "The role of STAT3 in keratinocyte defense is not restricted to viral infection, as Stattic treatment also prevented keratinocytes from responding to TLR ligands associated with bacterial infection." (PMID 25419841, 2014). "Other Genetic Forms of HIES/Combined Immunodeficiency (CID): Although conditions like DOCK8 deficiency (now classified as CID) can present with high IgE and eczema, our patient's history was dominated by bacterial and fungal infections without severe viral infections, aligning more with STAT3-HIES." (PMID 41458089, 2025). "However, the precise role of STAT3 signaling in the early step of viral infection is not yet fully understood." (PMID 37099596, 2023). "Taken together, our results showed that STAT3 activation in EV71-infected glia cells leads to upregulation of immune regulatory factors, which were tightly controlled, and revealed the detailed mechanism that STAT3 interfered with type I IFN-mediated antiviral response during viral infection." (PMID 31575039, 2019). "In the context of infection, it is generally produced by effector CD4 and CD8 T cells, and it acts via STAT3 signaling to downregulate expression of Th1 cytokines and CD4 T-cell activation, but can also have a variety of other diverse roles, especially during viral infection." (PMID 30641955, 2019). "However, to the best of our knowledge, there have been no reports describing the STAT3-dependent B cell response to an active, dynamic virus infection." (PMID 27486189, 2016).
viral infection (continued). "Notably, both pro- and antiviral functions of STAT3 have been documented and its precise role in the pathogenesis of viral infections is not yet fully established." (PMID 26199948, 2015). "Chicken cells over- expressing phospho STAT-3 showed marginal increase in viral nucleo-protein (NP) expression, significantly increased (p < 0.05) matrix gene mRNA expression and infectious virus release in culture supernatant at 24 h post H5N1-tyEng91 virus infection." (PMID 25431115, 2014). "Additionally, ASS1 expression affected STAT3 levels and its subcellular localization: ASS1 overexpression correlated with reduced nuclear STAT3 accumulation and increased viral replication, whereas ASS1 depletion promoted STAT3 nuclear translocation and restricted viral infection." (PMID 42037409, 2026). "While inhibition of Ec-STAT3 does not affect RGNNV replication, virus infection-induced vacuolation and autophagy are significantly increased." (PMID 31293595, 2019). "Unfortunately, no molecule directly targeting STAT3 has received Food and Drug Administration (FDA) approval for any pathology so far, and candidate compounds targeting viral disease have not advanced beyond preclinical evaluation." (PMID 29543893, 2018). "During viral infection, type I IFN signaling through IFNAR induces STAT1/STAT2 activity, but also leads to the induction of STAT3, which is thought to provide negative feedback keeping the IFN response under control." (PMID 30473701, 2018). "STAT3 knockdown enhanced NR2F6 expression, even in the cells without virus infection." (PMID 38829910, 2024). "In duck cells, by contrast, STAT-3 expression was significantly up-regulated (P < 0.05) by LPAI H2N3 and H5N1-tyEng91 virus infection; STAT-3 expression was not significantly affected (P > 0.05) by H5N1-tyTR05 virus infection." (PMID 25431115, 2014). "Indeed, in LNCaP-JAK1 cells, IFNγ activated STAT1 but not STAT3, abrogated NS3 production in EHDV-TAU-infected cells, and supported oncolysis by non-productive viral infection." (PMID 29441069, 2018).